NOX5 (NADPH oxidase 5)
Diseases named in the same sentence as NOX5 in open-access papers (continued):
Sharing a sentence is not in itself a finding about the gene and the disease.
melanoma (7 papers, 2014 to 2023). A malignant, usually aggressive tumor composed of atypical, neoplastic melanocytes. "Among the NOX family, NOX1 and NOX4 isoforms play a major role in melanoma, while NOX5 is also important but still scarcely studied." (PMID 35326089, 2022). "For example, NOX4 and NOX5 activities have been reported to be involved in the survival of human glioma, melanoma, and prostate cancer cells." (PMID 24911159, 2014). "At the cellular level, in vitro studies have confirmed that NOX5 promotes proliferation and survival and reduced apoptosis in prostate carcinoma cancer cells, breast cancer cells, lymphoma, Barrett esophageal adenocarcinoma cells, and melanoma." (PMID 36905456, 2023). "In melanomas, NOX1, NOX4, and NOX5 have been confirmed to be expressed, with NOX1 expression consistent throughout progression and NOX4 upregulated during metastasis." (PMID 35326683, 2022). "In this regard, we showed that 13% of the melanoma patients have alterations on NOX1 gene, 7% on NOX2, NOX3 and NOX5, and 15% on NOX4." (PMID 35326089, 2022). "As for NOX5, a recent study combined gene expression and flux balance analysis of BRAF-mutant melanomas to reveal the upregulation of NOX5 expression that is associated with the resistance to BRAF inhibitor treatment." (PMID 35326683, 2022). "Furthermore, these melanoma cells do not express NOX5, another NADPH oxidase isoform, which does not depend on any of the classical cytosolic NADPH oxidase subunits and is present in endothelial cells." (PMID 24911159, 2014).
breast carcinoma (6 papers, 2019 to 2024). "In breast cancer, it was observed that the expression of NOX5 is regulated by the transcription factor STAT5A, and depletion of NOX5 leads to a reduction in the invasive capacity of tumor cells." (PMID 39696702, 2024). "Using human colon and breast cancer cell lines in which the expression of NOX5 was depleted employing specific siRNAs, some works demonstrated the direct involvement of NOX5 in the migration or cell motility of those transformed cell lines." (PMID 36905456, 2023). "We found that the Nox1 and Nox5 mRNA levels of AWP1 KO breast cancer cell lines were significantly higher than those of WT cells and these enhancement of Nox1 and 5 were further induced by TNF-α exposure." (PMID 33816268, 2021). "The transcripts and proteins of NOX2 and NOX5 were distinctly expressed in breast cancer cells and mammospheres." (PMID 31019654, 2019). "However, NOX5 was confirmed to promote the proliferation of some tumor cells, such as breast cancer." (PMID 33889544, 2021).
lung cancer (6 papers, 2013 to 2024). A malignant neoplasm involving the lung. "It has been described that resveratrol induces the expression of the transmembrane enzyme NADPH oxidase-5 (Nox5) in lung cancer cells." (PMID 32492881, 2020). "We show here that the long form of NOX5 (NOX5-L) also promotes cell death, and thus determines the balance of proliferation and death, in skin, breast and lung cancer cells." (PMID 26513170, 2015). "Furthermore, we show that RV treatment markedly induces NAPDH oxidase-5 (Nox5) expression in both A549 and H460 cells, suggesting that RV may increase ROS generation in lung cancer cells through upregulating Nox5 expression." (PMID 23533664, 2013).
cardiac hypertrophy (5 papers, 2022 to 2024). "For instance, Ang II induces enhanced ventricular hypertrophy, interstitial fibrosis, and contractile dysfunction in a cardiomyocyte-specific NOX5 knock-in mouse model." (PMID 39456453, 2024). "Overexpression of human NOX5 in cardiomyocytes of rats exacerbated cardiac hypertrophy during heart failure, a pathological process that is mediated by intracellular Ca2+ level." (PMID 37566320, 2023). "Overexpression of calcium-regulated NOX5 isoform has been demonstrated to induce cardiac hypertrophy, fibrosis and dysfunction in transgenic NOX5 mice, worsening heart failure." (PMID 36012897, 2022). "The expression and functional significance of Nox5 in cardiac hypertrophy were recently studied using human cardiac tissues, transgenic mice, and neonatal rat cardiomyocytes." (PMID 35624741, 2022). "Furthermore, Nox5 overexpressing transgenic (Nox5-Tg) mice subjected to either TAC or Angiotensin II (AngII) infusion exhibited worsened cardiac hypertrophy and myocardial contractile dysfunction compared with TAC or AngII-treated wild-type (WT) mice." (PMID 35624741, 2022). "Moreover, since cardiomyocyte enlargement is the most defining characteristics of cardiac hypertrophy, Ca2+-dependent NOX5 was observed to exaggerate cardiac hypertrophy through ROS production." (PMID 36359731, 2022).
esophageal adenocarcinoma (4 papers, 2016 to 2024). A malignant tumor with glandular differentiation arising predominantly from Barrett mucosa in the lower third of the esophagus. "NOX5 has been further shown to support growth and cell proliferation via the PDGF-JAK2-STAT pathway in vascular smooth muscle cells, via the NFκB-COX2-PGE2 pathway in esophageal adenocarcinoma cells, and via the SHP2-tyrosine PO4 pathway in hairy cell leukemia." (PMID 29478325, 2019).
esophageal squamous cell carcinoma (4 papers, 2020 to 2023). Esophageal squamous cell carcinoma (ESCC) is a type of esophageal carcinoma (EC) that can affect any part of the esophagus, but is usually located in the upper or middle third. "NADPH oxidase 5 (NOX5) is a strong reactive oxygen species producer overexpressed in esophageal squamous cell carcinoma (ESCC) cells." (PMID 34459125, 2021). "NOX5 is overexpressed in clinical esophageal squamous cell carcinoma tumors, where NOX5-induced ROS may promote tumor development." (PMID 36670929, 2022). "In this study, we demonstrated that NOX5 was greatly upregulated in clinical esophageal squamous cell carcinoma (ESCC) tumors, ESCC cell lines or primary ESCC cells, and elevated NOX5 was correlated to malignancy of ESCC tumors and poor prognosis." (PMID 32792487, 2020).
Hyperglycemia (4 papers, 2014 to 2023). An increased concentration of glucose in the blood. "Intriguingly, immunoreactivity not only to NOX5 but also to NOX 4 was increased in retinal arterioles exposed to hyperglycemia, suggesting glucose-dependent upregulation of NOX4 and NOX5." (PMID 36829947, 2023). "Furthermore, in vitro studies have shown that high glucose increases Nox5 expression in renal cells and that silencing of Nox5 attenuates the hyperglycemia-induced increased expression of markers of inflammation and fibrosis via a reduction in ROS formation." (PMID 33396868, 2020). "Although sulodexide itself had only negligible antioxidant properties, it prevented hyperglycemia-induced overexpression of the pro-oxidant redox enzymes NOX4 and NOX5." (PMID 36829947, 2023). "Third, sulodexide prevented hyperglycemia-induced overexpression of the pro-oxidant enzymes, NOX4 and NOX5, in the vascular wall." (PMID 36829947, 2023). "Remarkably, sulodexide prevented hyperglycemia-induced NOX4 and NOX5 expression in the vascular wall, suggesting that this may be one of the mechanisms preventing ROS generation." (PMID 36829947, 2023).
Obesity (4 papers, 2021 to 2024). Accumulation of substantial excess body fat. "More recently, leptin has emerged as a potential activator of NOX5-derived ROS production in human epithelial mammary cells, linking obesity-associated hyperleptinemia with mammary tumorigenesis." (PMID 38542437, 2024). "Understanding the physiological and pathophysiological roles of vascular NOX5 in the development and progression of metabolic diseases is desirable since obesity and type 2 diabetes entail a greater risk of cardiovascular mortality." (PMID 33800461, 2021). "The same group reported that NOX5 expression in obesity led to elevated interleukin (Il-6) production, which results in upregulated thermogenesis and lipolysis in adipose tissue via upregulation of Pgc1α and Ucp1 expression." (PMID 37627585, 2023). "The aim of the present work is to describe the effect of endothelial NOX5 expression on neighboring adipose tissue in obesity conditions by using two systems." (PMID 35052534, 2021). "In summary, we have found that the expression of endothelial NOX5 in mice under obesity conditions increases the production of IL-6 in the endothelium." (PMID 35052534, 2021). "In summary, we found that the expression of NOX5 in the endothelium under obesity conditions is able to induce an upregulation of important insulin signalling intermediaries, such as Ir-B, Cav1, and Glut4 in the neighbouring adipose cells." (PMID 33800461, 2021). "A recent study from our group has proved that in mice, endothelial NOX5 expression under obesity conditions attenuates body weight gain, lipid accumulation and increases glucose uptake." (PMID 35052534, 2021). "However, studies in humanized NOX5 knock-in mice have given novel insights into the possible role of NOX5 in obesity." (PMID 37627585, 2023). "Thus, we report here that endothelial NOX5 expression under obesity conditions stimulates lipolysis by promoting AMPK phosphorylation mediated by IL-6 production." (PMID 35052534, 2021). "The role of NOX5 in obesity is, so far, not well characterized, particularly because the NOX5 gene is absent in rodents." (PMID 37627585, 2023).
renal fibrosis (4 papers, 2022 to 2024). A final common manifestation of a wide variety of chronic kidney diseases characterized by glomerulosclerosis and tubulointerstitial fibrosis. "For instance, in Akita transgenic mice expressing NOX5, renal fibrosis was primarily mediated by vascular smooth muscle cell- and mesangial cell-specific NOX5 expression." (PMID 39456409, 2024). "Importantly, this effect was also seen in non-diabetic mice lacking NOX4 expression, suggesting a more substantial role of NOX5 versus NOX4 in modulating EMT pathways leading to renal fibrosis." (PMID 38671844, 2024). "This is consistent with previous studies, where the silencing of NOX5 in human mesangial cells but not NOX4 led to the attenuation of high-glucose-induced upregulation of these markers of fibrosis, further highlighting the dominant role of NOX5 in exacerbating renal fibrosis in DKD." (PMID 38671844, 2024).
colon cancer (3 papers, 2023 to 2024). "Recent work has specifically implicated NOX5 in cell migration in colon cancer cell lines, coronary smooth muscle cells, and human brain microvascular endothelial cells." (PMID 36776559, 2023). "In this study, we demonstrated that PD treatment markedly induced ER stress and DNA damage by promoting NOX5-mediated ROS generation, thereby inhibiting the growth of colon cancer cells." (PMID 39850563, 2024). "Knocking down NOX5 attenuated the inhibition of proliferation and colony forming ability induced by PD in colon cancer cells and reversed the expression of C/EBP-homologous protein (CHOP) and activating transcription factor 4 (ATF4) proteins." (PMID 39850563, 2024). "To further determine the effect of NOX5 in colon cancer cells, we knocking down NOX5 expression by transfecting siRNAs." (PMID 39850563, 2024). "Knocking down NOX5 attenuated PD-induced ER stress and DNA damage, reversing the anti-CRC activity of PD, suggesting that NOX5 is a vital target of PD and mediates ROS-induced ER-stress and DNA damage in colon cancer cells." (PMID 39850563, 2024). "After transfection with siRNAs (siNOX5-1 and siNOX5-2) into colon cancer cells, NOX5 mRNA and protein levels were considerably downregulated in both RKO and LoVo cells." (PMID 39850563, 2024). "We demonstrated that PD synergizes with OXA to activate ER stress by upregulating NOX5 expression and induce DNA damage, thereby inhibiting the growth of colon cancer cells." (PMID 39850563, 2024). "NOX5 upregulation was also associated as a poor prognostic factor and worse prognosis in colon cancer patients, as the 5-year progression-free survival rate of NOX5-positive patients was significantly worse than that observed in NOX5-negative patients." (PMID 36905456, 2023). "Knockdown of NOX5 did not affect the proliferative and colony forming ability of colon cancer cells, but it attenuated the inhibitory effect of PD on cell viability and cell colony formation." (PMID 39850563, 2024). "The PD treatment significantly elevated both mRNA and protein levels of NOX5 in colon cancer cells, while did not significantly change the expression of NOX4 mRNA." (PMID 39850563, 2024). "Furthermore, silencing NOX5 reversed the elevation of ATF4 and CHOP following PD treatment, suggesting that NOX5 is a key mediator in the PD-induced ROS-mediated ER stress pathway in colon cancer cells." (PMID 39850563, 2024).
diabetic retinopathy (3 papers, 2021 to 2024). "NOX2, NOX4, and NOX5 have already been associated with the development of retinal vasculopathy in diabetic retinopathy and are also known to be expressed in human endothelial cells." (PMID 36829947, 2023). "The role of NOX5 in pathologically increased cell permeability and neovascularization in diabetic retinopathy is the subject of current research." (PMID 36829947, 2023).
essential hypertension (3 papers, 2019 to 2020). Hypertension that presents without an identifiable cause. "However, as the study concluded, the increased expression and activity of Nox5 in renal proximal tubules—that is caused, in part, by a defective renal dopaminergic system—may likely be responsible for oxidative stress, which contributes to the pathogenesis of primary hypertension in humans." (PMID 32823917, 2020).
pancreatic cancer (3 papers, 2020 to 2024). "Here we show that the calcium responsive NOX5 directly interacts with actin, and that this interaction has functional consequences both for NOX5 superoxide production as well as actin dynamics and cell migration of the pancreatic cancer cell line PSN-1." (PMID 36776559, 2023). "Finally, we show that knockdown of NOX5 in the pancreatic cancer cell line PSN-1 impairs cell migration." (PMID 36776559, 2023). "Using the pancreatic cancer cell line PSN-1, which express endogenous NOX5, we were also able to show that NOX5 expression is correlated with cell migration, a process which relies on coordinated restructuring of the actin cytoskeleton." (PMID 36776559, 2023).
Cerebral ischemia (2 papers, 2021 to 2022). Restriction of arterial blood supply to the brain associated with insufficient oxygenation to support the metabolic requirements of the tissue. "Upregulation of Nox1, Nox 4, and Nox5 occurs during brain endothelial aging, cerebral ischemia, and in the AD brain." (PMID 35813502, 2022). "Upon cerebral ischemia‐reperfusion, intracellular calcium increases, leading to the activation of NADPH oxidase 4(NOX4) and NOX5, two primary sources of oxidative stress." (PMID 34085418, 2021). "Drugs that selectively inhibit NOX4 (GKT136901) and NOX5(ML090) reduced BBB permeability, resulting in a significant reduction of infarct volume and direct neuroprotection when given immediately before or at the time of reoxygenation in a mouse model of cerebral ischemia‐reperfusion." (PMID 34085418, 2021).
cognitive deficit (2 papers, 2021 to 2022). "In the case of the MWM acquisition phase, the elderly groups, both Aged and Aged NOX5, showed cognitive deficit, because their escape latencies were significantly higher compared to the Control Young group." (PMID 34439558, 2021). "Indeed, specific Nox5 expression in endothelial cells leads to BBB permeability and cognitive deficits in aged mice, which supports the role of endothelial Nox5 in BBB dysfunction." (PMID 36290688, 2022).
esophageal cancer (2 papers, 2016 to 2024). A primary or metastatic malignant neoplasm involving the esophagus. "Thus, DOUX2 may also contribute to esophageal cancer in addition to NOX5, which was shown to promote cell proliferation in esophageal cancer." (PMID 26839536, 2016).
gastric cancer (2 papers, 2022 to 2024). A primary or metastatic malignant neoplasm involving the stomach. "Moreover, high expression of NOX4 and NOX5 were correlated to poorer overall survival in patients with end-stage gastric cancer." (PMID 38542437, 2024).
hairy cell leukemia (2 papers, 2019 to 2024). Hairy cell leukemia (HCL) is a rare type of leukemia in which abnormal B-lymphocytes are present in the bone marrow, spleen and peripheral blood. "This event was previously reported in primary cells of hairy cell leukemia, where SHP1 was found in cell membrane in close proximity to Nox5, which may oxidize and inactivate the phosphatase by generation of ROS." (PMID 30764849, 2019).
kidney damage (2 papers, 2019 to 2024). "Increased renal expression of NOX5 has been shown in diabetic individuals with nephropathy as well as in response to high glucose in key renal cell populations implicated in DKD, such as proximal tubular cells, podocytes, mesangial, and endothelial cells." (PMID 38671844, 2024).
type 2 diabetes mellitus (2 papers, 2021 to 2024). A type of diabetes mellitus that is characterized by insulin resistance or desensitization and increased blood glucose levels. "These associations can be explained by the fact that the influence of these factors is associated with enhanced production of ROS and oxidative stress, and thus potentiates the pro-oxidant effects of NOX5, increasing the risk of type 2 diabetes." (PMID 39529984, 2024). "This pilot study investigated whether single nucleotide polymorphisms (SNP) in the NOX5 gene (NADPH oxidase 5) are associated with the type 2 diabetes (T2D) risk." (PMID 39529984, 2024). "An experimental study in mice demonstrated that beta-cell-specific expression of Nox5 might be an important factor aggravating the high-fat diet-induced impairment of islet insulin secretion and β-cell failure in type 2 diabetes." (PMID 39529984, 2024).
abdominal aortic aneurysm (1 paper, 2022). Enlargement and ballooning of the vessel that supplies arterial blood to the abdomen, pelvis and legs. "The rather unexpected finding of this study was the clear causal role of endothelial Nox5 in type II25 abdominal aortic aneurysms under diabetic conditions." (PMID 35798762, 2022).
adenovirus infection (1 paper, 2022). "Finally, the cell cycle was detected to be altered by NOX5 adenovirus infection." (PMID 36358519, 2022).
anaplastic thyroid cancers (1 paper, 2015). "NOX1, NOX3, and NOX5 expression suggested minor changes in thyroid cancers, whereas the expression of NOX2 and NOX4 showed increased mRNA synthesis in papillary thyroid and anaplastic thyroid cancers." (PMID 26664298, 2015).
aortic aneurysm (1 paper, 2022). A ruptured aneurysm located in the wall of the proximal portion of the descending aorta proceeding from the arch of the aorta. "Instead, Nox5 may be an aggravating or even causal factor in the human diabetic complication of aortic aneurysms, which have a pre-/in-hospital mortality of 40–80%." (PMID 35798762, 2022).
asthenozoospermia (1 paper, 2025). "However, NOX5 has been associated with oxidative stress, a known culprit of male infertility, since over-expression of NOX5 was observed in asthenozoospermia." (PMID 39658334, 2025).
Barrett adenocarcinoma (1 paper, 2020). An adenocarcinoma arising from Barrett metaplastic epithelium in the esophagus. "Furthermore, the suppression of NOX5 in Barrett’s adenocarcinoma cells hinders proliferation and growth potential." (PMID 32575703, 2020).
cognitive decline (1 paper, 2021). "However, although there are other factors related to cognitive decline associated with aging as the expansion of glia cells, loss of neurons and attenuated vessel density, endothelial NOX5-dependent oxidative stress induced memory loss in the retention phase of the MWM in the knock-in aged mice." (PMID 34439558, 2021).
demyelinating disease (1 paper, 2016). A broad group of disorders that affect the myelin sheaths that cover the neurons. "Furthermore, NOX3 and NOX5, as inducers of OL differentiation, represent novel targets for therapies of demyelinating diseases, including multiple sclerosis, associated with impairment of OL differentiation." (PMID 27313511, 2016).